EDC4 (enhancer of mRNA decapping 4)
Description:
In the process of mRNA degradation, seems to play a role in mRNA decapping. Component of a complex containing DCP2 and DCP1A which functions in decapping of ARE-containing mRNAs. Promotes complex formation between DCP1A and DCP2. Enhances the catalytic activity of DCP2 (in vitro).
Synonyms: Hedls; RCD-8; Ge-1; GE1; HEDL5; RCD8
Tractability: PROTAC: ubiquitination databases record sites on it; its protein half-life has been measured.
Gene: Protein-coding gene on chromosome 16 (67,873,049 to 67,884,516, forward strand). Ensembl gene ENSG00000038358.
Subcellular location: Cytoplasm, P-body; Nucleus
Subcellular location (Human Protein Atlas): Cytoplasmic bodies; Nucleoplasm
Pathways (Reactome):
Metabolism of RNA: mRNA decay by 5' to 3' exoribonuclease
Gene Ontology:
Molecular function: protein binding
Biological process: deadenylation-dependent decapping of nuclear-transcribed mRNA; nuclear-transcribed mRNA catabolic process, deadenylation-dependent decay; deadenylation-independent decapping of nuclear-transcribed mRNA
Cellular component: cytoplasmic ribonucleoprotein granule; membrane; nucleoplasm; nucleus; P-body; cytoplasm; cytosol; RNA decapping complex
Genetic constraint (gnomAD): Loss-of-function variants: 64 observed, 159.5 expected, observed/expected ratio (o/e) 0.4, 90% interval 0.33 to 0.49. The upper end of that interval is the gene's LOEUF score, 0.49, which puts it in group 2 of 6, group 1 being the genes least tolerant of losing a copy. Missense variants: 1,303 observed, 1,862.8 expected, observed/expected ratio (o/e) 0.7, 90% interval 0.67 to 0.73. Synonymous variants: 684 observed, 735.67 expected, observed/expected ratio (o/e) 0.93, 90% interval 0.87 to 0.99.
Homologues: Orthologues: chimpanzee EDC4 (99% identical), macaque EDC4 (99% identical), rabbit EDC4 (96% identical), pig EDC4 (96% identical), mouse Edc4 (95% identical), dog EDC4 (95% identical), guinea pig EDC4 (95% identical), rat Edc4 (89% identical), tropical clawed frog edc4 (63% identical), zebrafish edc4 (61% identical), Drosophila melanogaster Ge-1 (24% identical), Caenorhabditis elegans edc-4 (14% identical).
Diseases named in the same sentence as EDC4 in open-access papers:
EDC4 is named in the same sentence as 17 diseases in open-access papers, as found by Europe PMC text mining. Sharing a sentence is not in itself a finding about the gene and the disease. The quoted sentences say what the papers report.
breast carcinoma (4 papers, 2018 to 2023). "Our present results indicate that EDC4 mutation carriers are more frequent in breast cancer cases than in controls, and, therefore, we propose to include EDC4 in larger sequencing studies." (PMID 29511213, 2018). "Our results indicate that all mutations identified in breast cancer cases are inside or near the WD40 domain of EDC4 at the N terminus of the protein." (PMID 29511213, 2018). "Lack-of-function mutations in EDC4 were detected in breast cancer." (PMID 37409345, 2023). "Thus, the ExAc frequency of EDC4 variants previously detected in breast cancer cases was of 0.14%, which is lower than the CIBERER Spanish dataset." (PMID 29511213, 2018). "Importantly, none of the mutants complemented ICL-induced hypersensitivity, cell cycle arrest, or chromosome fragility of EDC4 KO cells, indicating that all mutations found in breast cancer patients disrupt the function of EDC4 in DNA repair." (PMID 29511213, 2018). "Given the functional interaction of EDC4 with FA/BRCA components in HR-mediated repair, we investigated whether EDC4 is also mutated in breast cancer cases." (PMID 29511213, 2018). "In conclusion, our study demonstrates that EDC4 functionally phenocopies BRCA1, playing a role in HR-mediated DNA repair by regulation of end resection, and that germline mutations in EDC4 may confer risk of breast cancer." (PMID 29511213, 2018). "While additional genetic analysis in larger cohorts may be needed, our data suggest that rare variants in EDC4 may influence breast cancer susceptibility but lack a connection to FA." (PMID 29511213, 2018). "Here we observe that EDC4, besides its known role in processing-bodies (P-bodies), interacts with BRCA1 and is involved in HR-mediated DNA repair by regulating its end-resection step and that germline mutations in EDC4 may confer increased risk of breast cancer." (PMID 29511213, 2018). "In this context, it is interesting to note that EDC4, an integral component of P-bodies, has been implicated in IKK signaling as well as in breast cancer." (PMID 31426445, 2019). "In parallel, given the role of EDC4 in HR repair and the hypersensitivity of EDC4-depleted cell lines to PARP inhibition, our results suggest a therapeutic option for the treatment of EDC4-mutated breast cancers by synthetic lethality." (PMID 29511213, 2018). "Lack-of-function mutations in EDC4 were detected in BRCA1/2-mutation-negative breast cancer cases, suggesting a role in breast cancer susceptibility." (PMID 29511213, 2018).
cervical cancer (2 papers, 2020 to 2023). A primary or metastatic malignant neoplasm involving the cervix. "EDC4 overexpression reduced DNA damage caused by cisplatin and enhanced cell growth of cervical cancer cells." (PMID 33054858, 2020). "A 2020 study showed that deleting EDC4 (Enhancer of mRNA decapping protein 4) in cervical cancer cells enhanced sensitivity to cisplatin and inhibited cell proliferation produced via cisplatin and DNA damage." (PMID 37176052, 2023). "Two human cervical cancer cell lines, HeLa and SiHa, were used to investigate the role of EDC4 on cisplatin resistance in vitro." (PMID 33054858, 2020). "EDC4 knockdown in cervical cancer cells (HeLa and SiHa) enhanced cisplatin sensitivity and cisplatin induced cell growth inhibition and DNA damage." (PMID 33054858, 2020). "The present results showed that EDC4 knockdown in two cervical cancer cell lines enhanced cisplatin sensitivity by enhancing cisplatin induced cell growth inhibition and DNA damage, which was in accordance with previous report." (PMID 33054858, 2020). "In conclusion, the present results indicated that EDC4 is responsible for the cisplatin resistance partly through interacting with RPA in cervical cancer by alleviating DNA damage." (PMID 33054858, 2020). "The present results indicated that EDC4 is responsible for the cisplatin resistance partly through interacting with RPA in cervical cancer by alleviating DNA damage." (PMID 33054858, 2020). "This study indicated that EDC4 or RPA may be novel targets to combat chemotherapy resistance in cervical cancer." (PMID 33054858, 2020). "To investigate whether EDC4 is related with cisplatin sensitivity, we depleted EDC4 in two human cervical cancer cell lines (HeLa and SiHa) by short hairpin RNA (shRNA) of two independent shRNA sequences (shEDC4#1 and shEDC4#2)." (PMID 33054858, 2020). "As the present results showed that EDC4 reduced the cisplatin sensitivity in cervical cancer cells and cisplatin induced DNA damage, we speculate whether the effect of EDC4 is related to RPA." (PMID 33054858, 2020). "In addition, EDC4 overexpression reduced the cisplatin induced DNA damage and enhanced cell growth of cervical cancer cells." (PMID 33054858, 2020).
viral infection (2 papers, 2016 to 2025). "The importance of the VP35-EDC4 interaction to the viral infection cycle was evaluated by depletion of EDC4 protein with two distinct siRNAs and then challenge with EBOV." (PMID 41006235, 2025).
leukemia (1 paper, 2015). A malignant (clonal) hematologic disorder, involving hematopoietic stem cells and characterized by the presence of primitive or atypical myeloid or lymphoid cells in the bone marrow and the blood. "Similar results were obtained in U937 leukemia cells under M1-skewing conditions, in which a decrease in EDC4 or Dcp1a expression suppressed the IL-6 production without severely altering the mRNA level." (PMID 25970328, 2015).
oral cancer (1 paper, 2019). "In conclusion, next-generation sequencing analysis revealed that a total of 13 genes (RRP43, RRP42, CSL4, TRF4, Mtr4, RRP6, MPP6, CNOT2, CNOT3, SKI2, Ski3, EDC4, and XRN1) involved in the mRNA degradation pathway were upregulated by PPARα activation in oral cancer cells." (PMID 31724941, 2019).
ovarian carcinoma (1 paper, 2023). A malignant neoplasm originating from the surface ovarian epithelium. "The same trend of changes in the POM121, EDC4, and SNRPC genes was also found in ovarian cancer." (PMID 37409345, 2023).
Sjögren’s syndrome (1 paper, 2020). "Ge-1, a ~160 kDa protein also known as HEDLS and EDC4, was initially identified as an autoantigen in a patient with Sjögren’s syndrome (SjS) in 1994." (PMID 32776893, 2020).
cancer (5 papers, 2016 to 2024). A tumor composed of atypical neoplastic, often pleomorphic cells that invade other tissues. "Study of the role of ubiquitination in EDC4 regulation and identification of the responsible ubiquitin ligase may further decipher the role of this protein in DNA repair and its link to cancer susceptibility." (PMID 29511213, 2018). "Taking together our results suggest that EDC4 is a functional phenocopy of BRCA1 that could be targeted in cancer therapeutics." (PMID 29511213, 2018). "Therefore, independent observations further suggest a role for altered EDC4 function in cancer development and/or progression." (PMID 29511213, 2018). "Cisplatin decreased the amount of the colony of cancer cells, but was reversed by EDC4 overexpression (Vector + DDP vs. EDC4 + DDP, p < 0.05 for HeLa, p < 0.01 for SiHa)." (PMID 33054858, 2020). "EDC4 depletion decreased the IC50 of cisplatin of HeLa (from 9.728 μM to 5.226 μM) and SiHa cells (from 25.29 μM to 9.423 μM), which indicated that the cancer cells were more sensitive to drug in terms of cell survival." (PMID 33054858, 2020).
infection (4 papers, 2012 to 2025). The state of being infected such as from the introduction of a foreign agent such as serum, vaccine, antigenic substance or organism. "Higher level expression of VP35 seen in advanced stages of infection also caused loss of EDC4 puncta associated with DDX6, a marker of P-bodies, suggesting disruption of normal P-body organization." (PMID 41006235, 2025). "In our work, markers of P-bodies such as DDX6 and EDC4 formed several large puncta in the cytoplasm of uninfected cells that were replaced with smaller, more numerous puncta later in infection." (PMID 41006235, 2025). "Overall, these observations show that VP35 interacts with the C-terminal half of EDC4, and overexpression of the distal domain disrupts infection likely through interaction with VP35." (PMID 41006235, 2025). "Furthermore, expression of the EDC4 distal domain acted in a dominant-negative manner, impairing infection." (PMID 41006235, 2025). "Then we observed the dot-like staining of QKI in the cytoplasm, there’re co-localizations of QKI and EDC4 (P-body biomarker) in the cytoplasm of RAW264.7 cells, and the QKI was dramatically decreased after infection." (PMID 36088389, 2022). "To evaluate whether EBOV replication depends on decapping components other than EDC4, we tested the impact of knockdowns of DCP1A, B and DCP2 and accessory decapping protein EDC3 on infection efficiency." (PMID 41006235, 2025). "Since overall cellular EDC4 levels trended upwards but were not significantly different between uninfected and infected cells, the EDC4 in cells is therefore redistributed during infection." (PMID 41006235, 2025).
EDC4 also shares sentences with these, for which no sentence is quoted: metastatic disease (2 papers); tumor (2); autoimmune conditions (1); genital herpes (1); hepatitis C virus infection (1); lung carcinoma (1); promyelocytic leukemia (1); serous ovarian cancer (1).